KRAS (KRas proto-oncogene, GTPase)
Diseases named in the same sentence as KRAS in open-access papers (continued):
Sharing a sentence is not in itself a finding about the gene and the disease.
tumor (continued). "The YAP1-promoting tumor activity is probably attributed to the activation of TGF-β, Hedgehog, or KRAS signaling pathways." (PMID 36479120, 2022). "Targeting individual KRAS-mediated factors may provide therapeutic insights and understanding the cooperative interactions between different transcriptional and signaling networks remains an essential need to target the heterogenous tumor cell population of KRAS-driven PDAC effectively." (PMID 35800049, 2022). "Various studies have uncovered a KRAS/IL-8 link mediated by the MAPK or PI3K/AKT signaling pathways in different human cancer cell lines and tumor specimens." (PMID 35965494, 2022). "Colon cancer cells transfer mutant KRAS to the neutrophils through exosomes, thereby promoting NETosis through the upregulation of IL8 which subsequently induces tumor growth, invasion and migration." (PMID 35574410, 2022). "The efficacy of nanoparticles containing KRAS-targeting small interfering RNA (siRNA) has been tested in mouse models and the results suggest that targeting KRAS-mutant cells through specific siRNA might be effective for oncogene silencing and inhibition of tumor growth." (PMID 35456940, 2022). "For the KRAS, NRAS, and BRAF V600E genes, the concordance rates between the tumor tissue test by PCR and ctDNA test by NGS were 86.4%, 86.4%, and 100%, respectively." (PMID 35280779, 2022). "Peripheral blood lymphocytes (PBL) transduced with these TCRs can recognize several HLA-A*11:01-positive KRAS mutant human PDAC cell lines and suppress xenograft tumor growth." (PMID 35966590, 2022). "As a major downstream part of KRAS signaling, the Ras/Raf/MEK/ERK pathway plays a pivotal role in tumor initiation, progression, and differentiation." (PMID 35305624, 2022). "A simple mutation of the KRAS gene (most often at codons 12 or 13) can induce constitutive activation of the KRAS protein independently of the EGFR, inducing tumor growth." (PMID 35740495, 2022). "It seems that the KRAS activation of JNK has a critical role in the maintenance of the self-renewal and tumor-initiating capacity of pancreatic CSCs/CSLCs." (PMID 36232313, 2022). "As ZNF24 has been proven to promote the growth of SLC7A5-mediated KRAS mutant LUAD cells in vitro, we established a nude mouse transplanted tumor model for in vivo experimental verification." (PMID 36505791, 2022). "The hypomethylation of KRAS in BLCA, READ, and COAD is low compared to their normal counterparts, which matched the low level of KRAS in these tumor cohorts." (PMID 35563733, 2022). "Factors significantly prognostic for OS in the GSE72094 dataset included risk score based on the four autophagy-immune-related genes, as well as patient gender and tumor TNM stage, KRAS status, and EGFR status." (PMID 36177001, 2022). "Among the enriched pathways in the NACT group, KRAS signaling and WNT/beta-catenin signaling are notably connected to oncogenic potential and tumor progression." (PMID 35892848, 2022). "A multivariate analysis was performed including tumor and nodal classification, grade, PAM50 subtype, NF1, KRAS, RAF1, and JUN alterations." (PMID 36358725, 2022).
tumor (continued). "In an in vivo KRAS G12C CDX model of PDAC, increased efficacy of selinexor and sotorasib combination in suppressing tumor growth and enhancing survival has been observed." (PMID 35573474, 2022). "To further explore the effect of chr1q amplifications in KRAS wildtype PDAC, we performed mass spectrometry (MS)-based proteome profiling of PanGen patient tumor samples." (PMID 36209277, 2022). "In a mutant KRAS lung adenocarcinoma model, conditional MYC amplification led to increased expression of IL-23 by tumor cells that inhibited recruitment of intra-tumoral B, T and natural killer (NK) cells." (PMID 33917037, 2021). "It was observed that knockdown of the glutamine transporter in KRAS mutant CRC cells resulted in decreased cell proliferation, migration and invasion, as well as tumor formation and metastasis in vivo." (PMID 34200820, 2021). "Of the 1117 patients included, 420 (38%) had KRAS mut tumours, 142 (13%) had EGFR mut tumours, 12 (1%) had ALK rearranged tumours, and 3 (0.3%) patients had ROS1 rearranged tumours." (PMID 34503114, 2021). "In addition to MEK inhibitors, a recent study revealed that a covalent KRAS inhibitor could inhibit tumor cell growth in NSCLC with KRAS G12C mutation, but not in CRC." (PMID 33982211, 2021). "Among the 9789 CRC cases with tumor data available, 11% of the tumors were BRAF-mut, 34% KRAS-mut, 15% MSI-H, and 18% CIMP+." (PMID 34377935, 2021). "In these 76 patients, genomic profiling of 128 tumors by MSK-IMPACT yielded a median of 8 somatic alterations per tumor (range, 1–47), and a major oncogenic driver alteration (e.g., EGFR, KRAS, ALK, ROS1, or MET exon 14) was identified in 107 tumors (84%)." (PMID 34359558, 2021). "In summary, PET-CT is a direct demonstration of tumor metabolism but still cannot uncover the strong relationship between the parameters of SUV and KRAS status based on the current evidence." (PMID 34026605, 2021). "Recently, a study reported that exosome released from tumor cells, which contained KRAS protein, drive TAM polarization, thus promoting tumor growth." (PMID 34925244, 2021). "Recent clinical trials of G12C allele-specific inhibitors revealed high dose tolerance and effective tumor reduction in certain patients, supporting selective inhibition of RAS mutants as a viable therapeutic strategy against KRAS(G12C)-driven cancer." (PMID 33976200, 2021). "This line of investigation also demonstrated that the KRAS protein levels in tumors that originated in the EF1-tTA-based transgenic model (i.e., tumor samples a–c) were similar to those tumors that express mutant KRAS from the endogenous locus." (PMID 34145248, 2021). "To challenge this concept, we analysed the impact of the genetic alterations (on KRAS, PIK3CA, PTEN) and of the organ of origin in determining the role of each class I PI3K in tumour cell migration and cytotoxic sensitivity in response to PI3K inhibitors." (PMID 34033220, 2021). "In our 100 stage II LVI+ patients, LVI was significantly correlated with pT stage, degree of differentiation, tumor stage, serum CEA and CA19-9 levels, KRAS status, TB, and PNI." (PMID 33866973, 2021). "Among them, SHC1, FKBP4, NRAS, KRAS had higher expression, and PRKCD, ADCY9 had lower expression in LUAD tumor tissues compared with normal tissue." (PMID 33936178, 2021).
tumor (continued). "Another distinctive feature of KRAS-G12D protein is that it can be released by PDAC cells into the tumor microenvironment and then mediates the polarization of pro-tumor macrophages." (PMID 34607583, 2021). "In tumor tissue developed from ‘transformed’ NIH-3T3 cells, mutant sequences of the KRAS gene were found." (PMID 34830126, 2021). "Mutant KRAS drives PDAC development and promotes tumour cell proliferation via altered metabolic pathways including stimulation of glucose uptake and utilization, reprogrammed glutamine metabolism and increased autophagy." (PMID 33452856, 2021). "This research was aimed at analyzing the relative levels of KRAS and HRAS genes mRNA expression in whole blood samples in parallel with tumor tissue and, what is an innovative approach, at three points of time during the patients’ observation." (PMID 33549031, 2021). "Two independent organoid lines were tested, C001 and C002, both are KRAS WT, both express high levels of RAC1B compared to the stage 3 invasive tumour utilised above and both show resistance to cetuximab treatment in vitro." (PMID 33879799, 2021). "Based on these preliminary data, several trials combining MEK inhibitors and hydroxychloroquine in KRAS and NRAS mutant tumours have started." (PMID 34200676, 2021). "WEE1 and mTOR inhibitor induced efficient apoptosis in KRAS-mutant NSCLC cell lines and suppressed tumor growth in mice model." (PMID 34301278, 2021). "For these reasons, the KRAS status of liquid biopsy tends to be less reflective in NRAS, BRAF, EGFR, and MSI of the origin tumor." (PMID 34442609, 2021). "Biochemical analyses further demonstrate that CXCL12 supports KRAS-induced MAPK and AKT signaling to promote tumor cell survival and proliferation." (PMID 35008248, 2021). "Since miR-134 targets and inactivates KRAS, Nanog mRNA, HNF4α, EGFR, ITGB1, and FOXM1, it also inhibits tumor invasion and metastasis." (PMID 33331954, 2021). "It has also been found that KRAS mutant pancreatic ductal adenocarcinoma showed resistance to MEK inhibition and activated mTORC1 and mTORC2, which are key effectors of tumor growth." (PMID 34830283, 2021). "The therapeutic index of pan-RAS inhibitors will depend on the effects of targeting mutant RAS (KRAS, HRAS or NRAS) oncogene addiction in tumour cells compared to the effect on normal cells when activated RAS is inhibited." (PMID 33462327, 2021). "There are three genes related to human tumours in the RAS gene family, Harvey rat sarcoma viral oncogene (HRAS), KRAS, and Neuroblastoma rat sarcoma viral oncogene (NRAS), which are located on chromosomes 11, 12, and 1, respectively." (PMID 34012925, 2021). "The administration of si-KRAS and anti-miR-210 loaded in cholesterol NPs in an in vivo model modulated the TME, led to a delay of tumor growth and inhibition of metastasis, and prolonged survival." (PMID 33923200, 2021). "Mechanistically, KRAS drives the production of CSF2 and lactate in tumor cells by stabilizing hypoxia-inducible factor-1α (HIF-1α), a transcription factor that controls the expression of CSF2 and glycolytic genes." (PMID 33833221, 2021).
tumor (continued). "In several tumor tissue studies, miR-143-3p was significantly downregulated and acted as a tumor suppressor by silencing genes which promoted cell proliferation and invasion, i.e., COX-2 in gastric cancer, FOSL2 in osteosarcoma, and KRAS in PitNET." (PMID 33808624, 2021). "AZD0364 exhibited dose- and time-dependent modulation of ERK1/2-dependent signaling to result in tumor regression in sensitive BRAF-and KRAS-mutant xenografts." (PMID 34301278, 2021). "Given that the EMT process is reversible, tumor cells may switch back and forth between epithelial and mesenchymal status in early tumorigenesis before transforming into a more permanent mesenchymal state after activating bypass signaling networks that permit full independence from KRAS." (PMID 34680229, 2021). "CD44 was found to critically contribute to activating the oncogenic KRAS signalling pathway through the MAPK pathway in lung adenocarcinoma cell lines, hence promoting tumour cell proliferation and survival." (PMID 34944493, 2021). "In 2016, Tape and colleagues reported that PDAC tumor cell mutant KRAS (KRASG12D) signals reciprocally through stromal cells, to subsequently enhance tumor cell function." (PMID 34298706, 2021). "Moreover different clinical studies have suggested that the dysbiotic signature of CRC might be different according to the tumor characteristics (KRAS, BRAF mutations, and DNA mismatch repair MMR alterations) and/or tumor sidedness (proximal or distal location)." (PMID 34063108, 2021). "Next, we explored the roles of BLT2 and 5-/12-LOX in transgenic mice with lung-specific expression of mutant KRAS (KrasG12D) and observed that BLT2 or 5-/12-LOX inhibition decreased IL-6 production and tumor formation." (PMID 34635780, 2021). "In a preclinical setting, LY3009120 displayed an anti-proliferative effect in KRAS-mutant CRC cell lines and inhibited tumor growth in KRAS-mutant xenograft models." (PMID 34742312, 2021). "Pre-clinical models showed that the combination of the SOS1:KRAS and MEK inhibition resulted in tumor regression." (PMID 34845311, 2021). "In our current study, a SNP in the tumor budding pathway, MMP2 rs243865, was a strong predictor of OS in KRAS mutant patients." (PMID 34108518, 2021). "Patient-derived xenograft (PDX) models were used to investigate the anti-tumor effects of RGS in RAS wild-type and KRAS-mutant CRC patients." (PMID 34347396, 2021). "Pertinently to the topic of this review, clinical trials for KRAS mutant PDAC with momelotinib, were unsuccessful, despite being effective in reducing tumor burden in a KrasLSLG12D/WT–induced lung cancer model." (PMID 34572737, 2021). "Of note, evidence exists which indicates that interconversion of PDAC cells from a classical to a squamous phenotype might also occur spontaneously in association with the acquisition of a major imbalance of KRAS during metastatic progression of a tumor, in the absence of other stimuli." (PMID 34503261, 2021). "However, that KRAS mutation was not identified in the tumor tissue." (PMID 33915745, 2021). "In preclinical experiments, MRTX849 inhibited KRAS downstream signaling and tumor growth in patient-derived xenograft models from KRASG12C mutant tumor cells." (PMID 34830024, 2021). "KRAS amplification and homozygous deletion in PTEN and RB1 were detected in tumor samples collected from the patient." (PMID 33670958, 2021). "Owing to the fact that the clinical efficacy of AUY922 remains poor in monotherapies, it has been synergized with trametinib in KRAS-mutant NSCLC and represented a potent anti-tumor activity both in vitro and in vivo." (PMID 34946644, 2021).
tumor (continued). "Oncogenic KRAS signaling has been reported to play a predominant role in multiple aspects of PDAC metabolism, including adaptive metabolic responses and PSC-tumor cell interplay." (PMID 33546284, 2021). "Tumours that escape treatment trough HDAC5, showed a prominent neutrophil-to-macrophage phenotype as compared to oncogenic KRAS-driven tumours." (PMID 33671588, 2021). "SCH53239 and SCH54292 compounds act exactly in this way, by maintaining KRAS in the GDP-bound inactive state, with the arrest of the proliferation of tumor cells." (PMID 34440587, 2021). "Specific to our study, important tumor factors such as MSI, LVI, and KRAS status have only been collected since 2010, limiting the length of follow-up available for analysis." (PMID 34650170, 2021). "As such, we conducted cost-effective analyses to compare anti-EGFR mAb versus bevacizumab in KRAS, pan-RAS WT patients, and the subgroup of left-sided pan-RAS WT tumor." (PMID 34012917, 2021). "A striking feature of KRAS KO tumor cells was a significant 2–10-fold increase in MHC gene expression (H2d1, H2k1, B2m, and H2-aa, H2-ab1, CD74) over KRAS intact controls." (PMID 33674596, 2021). "Kobe0065, the most promising compound they developed, was proven to bind to RAS-GTP (HRAS and KRAS) and competitively block RAF binding, which inhibited the growth of cancer cells carrying activated RAS oncogenes and tumor xenografts." (PMID 34742312, 2021). "Although KRAS-mutant signaling plays an important role in tumorigenesis, only signaling through the PI3K/AKT pathway seems to be necessary for the maintenance of tumor growth." (PMID 34177761, 2021). "Conversely, the higher rate of co-occurrent alterations, either “passengers” or even “drivers”, in MET, KRAS, BRAF and EGFR-driven tumors, suggests a branched clonal evolutionary process existing from the early steps of tumor progression." (PMID 33946519, 2021). "However, changes from squamous PDAC toward a less aggressive (classical) disease phenotype might only be achieved when a tumor shifts from a major KRAS imbalance that disappears after therapy, due to subsequent outgrowth of minor clone(s) that carry no KRAS imbalance." (PMID 34503261, 2021). "We conclude that mutant KRAS and BRAF impact the intrinsic sensitivity of tumor cells to chemotherapy and targeted therapy." (PMID 34771595, 2021). "IN10018 (25 or 50 mg kg‐1, p.o., daily) conferred strong tumor growth inhibition effects against multiple CDX and PDX KRAS mutant tumors in vivo." (PMID 34151545, 2021). "We found that CRC cells harboring mutant KRAS have a selective advantage to actively reprogram macrophages to a TAM-like phenotype, which in turn induces resistance of the tumor cells to cetuximab and promotes malignant progression." (PMID 33833221, 2021). "Firstly, several vital prognostic factors, such as KRAS, BRAF, microsatellite instability (MSI), tumor regression grade, circumferential resection margin (CRM), were inaccessible in the SEER database, thus did not incorporate in the proposed nomogram." (PMID 34322745, 2021). "Current guidelines for the therapeutic management of patients with mCRC recommend KRAS, NRAS, BRAF and high microsatellite instability (MSI-H) profiling on tumor tissue samples." (PMID 34943612, 2021). "This transient spike in ctDNA was reported previously for KRAS and EGFR in NSCLC, probably reflecting tumor DNA release by death of tumor cells upon initiation of systemic treatment." (PMID 34449963, 2021).